CCPG1 (cell cycle progression 1)
Description:
Acts as an assembly platform for Rho protein signaling complexes. Limits guanine nucleotide exchange activity of MCF2L toward RHOA, which results in an inhibition of both its transcriptional activation ability and its transforming activity. Does not inhibit activity of MCF2L toward CDC42, or activity of MCF2 toward either RHOA or CDC42 (By similarity). May be involved in cell cycle regulation.
Synonyms: CPR8; KIAA1254
Tractability: Small molecule: a structure with a bound ligand is known. Antibody: UniProt predicts a signal peptide or a membrane-spanning region. PROTAC: ubiquitination databases record sites on it; its protein half-life has been measured.
Gene: Protein-coding gene on chromosome 15 (55,340,032 to 55,408,510, reverse strand). Ensembl gene ENSG00000260916.
Subcellular location: Cytoplasmic granule membrane
Subcellular location (Human Protein Atlas): Golgi apparatus; Endoplasmic reticulum
Gene Ontology:
Molecular function: protein binding
Biological process: positive regulation of cell cycle; positive regulation of cell population proliferation; reticulophagy
Cellular component: membrane
Genetic constraint (gnomAD): Loss-of-function variants: 32 observed, 55.29 expected, observed/expected ratio (o/e) 0.58, 90% interval 0.44 to 0.78. The upper end of that interval is the gene's LOEUF score, 0.78, which puts it in group 3 of 6, group 1 being the genes least tolerant of losing a copy. Missense variants: 725 observed, 781.79 expected, observed/expected ratio (o/e) 0.93, 90% interval 0.87 to 0.99. Synonymous variants: 270 observed, 260.02 expected, observed/expected ratio (o/e) 1.04, 90% interval 0.94 to 1.15.
Homologues: Orthologues: chimpanzee CCPG1 (99% identical), macaque CCPG1 (94% identical), rabbit CCPG1 (85% identical), dog CCPG1 (81% identical), pig CCPG1 (78% identical), rat Ccpg1 (70% identical), mouse Ccpg1 (70% identical), guinea pig CCPG1 (55% identical), tropical clawed frog ccpg1 (51% identical).
Diseases named in the same sentence as CCPG1 in open-access papers:
CCPG1 is named in the same sentence as 8 diseases in open-access papers, as found by Europe PMC text mining. Sharing a sentence is not in itself a finding about the gene and the disease. The quoted sentences say what the papers report.
pancreatic cancer (2 papers, 2018). "In vivo, CCPG1 is required to maintain the health of pancreatic acinar cells and, as such, future work in disease-state scenarios, such as pancreatic cancer formation, which is regulated by autophagy status, will further illuminate the role of CCPG1 and reticulophagy in health and disease." (PMID 29916296, 2018). "Speculatively, contexts where this manipulation of such functions of CCPG1 might be beneficial might be the amelioration of ER stress in pancreatic inflammatory states or, conversely, the enhancement of ER stress and elimination of malignant cells in pancreatic cancers." (PMID 29290589, 2018).
colorectal cancer (1 paper, 2023). A primary or metastatic malignant neoplasm that affects the colon or rectum. "Expression analysis by means of quantitative PCR validated the inverse correlation between miR-1183 and CCPG1 in colorectal cancer tissues." (PMID 37540697, 2023).
glioma (1 paper, 2011). A benign or malignant brain and spinal cord tumor that arises from glial cells (astrocytes, oligodendrocytes, ependymal cells). "For example, lower amounts than expected regarding mRNA levels are noted for MDH1 in GBM and SIRT1 in gliomas; or the protein concentration was increased in glioma tissues, although the mRNA was only slightly modified (typically CCPG1, BCL2, MDM2 and PTBP1)." (PMID 21655185, 2011).
melanoma (1 paper, 2022). A malignant, usually aggressive tumor composed of atypical, neoplastic melanocytes. "Only five genes were found to be predictive of good outcome when highly expressed in melanoma: LYSMD2, PSPIP2, SNAP23, TSHR, and CCPG1." (PMID 36553569, 2022).
tumor (2 papers, 2022). "CCPG1 also acts as a tumor suppressor in retinoblastoma, probably related to cell apoptosis and proliferation." (PMID 35327508, 2022). "Cell Cycle Progression 1 (CCPG1) is involved in endoplasmic reticulum homeostasis and may be a tumor suppressor gene." (PMID 36553569, 2022). "It is speculated that FAM134B, CCPG1, and TEX264 are receptors for common ER-phagy in tumor development, while SEC62 may be more significant in the recovery process after anticancer compound treatment, and RTN3L may have a hand in the degradation of the tubular ER." (PMID 35327508, 2022).
cancer (1 paper, 2018). A tumor composed of atypical neoplastic, often pleomorphic cells that invade other tissues. "For example, the recently identified ERphagy receptor CCPG1 has been linked to prostate cancer and in fact was proposed as a predictive biomarker for this type of cancer." (PMID 30250843, 2018).
CCPG1 also shares sentences with these, for which no sentence is quoted: dyslexia (1 paper); keloid (1).